NR1H3 (nuclear receptor subfamily 1 group H member 3)
Diseases named in the same sentence as NR1H3 in open-access papers (continued):
Sharing a sentence is not in itself a finding about the gene and the disease.
breast carcinoma (continued). "To investigate the expression of three genes, NR1H3, PLEKHA4, and THEM6, in breast carcinoma, we analyzed multiple independent cohorts, including three GEO cohorts as well as the cBioPortal database." (PMID 38081884, 2023). "Moreover, NR1H3 may function as a predictor of chemoresponsiveness in breast cancer." (PMID 36699456, 2022). "In summary, our study showed that low NR1H3 expression was correlated with worse survival, especially for basal subtype, HER2 positive subtype and grade 3 breast cancer patients." (PMID 36699456, 2022). "In order to verify the findings from the database, we detected the protein level of NR1H3 and macrophage marker CD68 in paraffin tissue microarrays from breast cancer patients by IHC." (PMID 36699456, 2022). "Our results revealed the important role of NR1H3 in TME as well as providing a potential relationship between NR1H3 and tumor-immune interactions in breast cancer." (PMID 36699456, 2022). "Correlation of NR1H3 gene expression with OS, RFS, DMFS and PPS in breast cancer with different clinicopathological features." (PMID 36699456, 2022). "Compared with high NR1H3 expression, low expression of NR1H3 indicated a worse survival prognosis of OS (p = 0.047), RFS (p = 3e-04) and PPS (p = 0.033) in HER2-positive breast cancer." (PMID 36699456, 2022). "As a kind of nuclear receptor superfamily, the liver X receptor (LXR) family, including LXRα (LXRA, NR1H3) and LXRβ (LXRB, NR1H2), is an important regulator of several kinds of cancers (prostate cancer, breast cancer, etc.)." (PMID 30770793, 2019). "In mouse breast-cancer models, 27-hydroxycholesterol augments ER-dependent mammary-tumor growth and increases NR1H2/NR1H3-dependent metastasis." (PMID 26894976, 2016). "APOL3, APOL4, NR1H3, OSBPL1A, MAP2K6, and ZDHHC8 were protective genes for breast cancer prognosis." (PMID 35919504, 2022). "Moreover, low NR1H3 expression was correlated with poorer prognosis of RFS in basal (p = 5.3e-6), luminal A (p = 3.0e-4), luminal B (p = 0.002) and HER2+ breast cancer patients (p = 0.0003)." (PMID 36699456, 2022). "Similarly, the poor prognosis in breast cancer (OS p = 0.007; RFS p = 1.9e-8; DMFS p = 0.004; PPS p = 0.011) was shown to correlate with lower NR1H3 expression." (PMID 36699456, 2022). "The data obtained in these mouse models contrast with the observations made in some breast-cancer cells, where NR1H2/NR1H3 activation reduces proliferation with down-regulation of genes involved in cell cycle progression, DNA replication and other cell-growth-related processes." (PMID 26894976, 2016). "NR1H3 is a nuclear receptor component and an anti-invasive gene for bladder cancer; PARP12 has been reported to suppress hepatocellular carcinoma metastasis; SAMHD1 is yet another suppressor of epithelial transformation; PSMB9 is a key metastasis suppressor for breast cancer." (PMID 33562461, 2021). "For patients treated with FAC (Fluorouracil, Adriamycin, Cytoxan), high NR1H3 expression predicted pathological response in luminal A and HER2 negative breast cancer." (PMID 36699456, 2022). "In addition, NR1H3 was highly expressed in pathological responders receiving FEC (Fluorouracil, Epirubicin, Cyclophosphamide) treatment in grade 1 breast cancer patients and Ixabepilone treatment in HER2 negative patients." (PMID 36699456, 2022).
Hepatic steatosis (12 papers, 2015 to 2023). Steatosis is a term used to denote lipid accumulation within hepatocytes. "Notably, NR1H3 signaling is associated with liver diseases such as hepatic steatosis." (PMID 37893992, 2023). "In addition, it could affect the development of pathogenic conditions, including hepatic steatosis, and increase the hepatic triglyceride content; the inhibition of NR1H3 contributes to the recovery from hepatocyte steatosis." (PMID 31121974, 2019). "Among lipogenesis-related transcription factors, SREBP1 and NR1H3 (LXR) genes were elevated in liver tissues of hepatic steatosis patients, but MLXIPL (ChREBP) genes remained unchanged." (PMID 32332706, 2020). "Conversely, over-expression of nr1h3 in enterocytes confers protection from dyslipidemia and hepatic steatosis when animals are fed a high fat diet." (PMID 25556679, 2015). "Zebrafish bearing a targeted deletion mutation of the master transcription factor of cholesterol catabolism Liver x receptor alpha (nr1h3) gene develop severe hypercholesterolemia and hepatic steatosis when fed high-cholesterol and high-fat diets." (PMID 25556679, 2015).
dyslipidemia (9 papers, 2009 to 2025). "NR1H3 also plays numerous roles in pathways involved in metabolic syndrome." (PMID 29190701, 2017).
diabetes (5 papers, 2011 to 2023). "At 3 months, fructose feeding induced upregulation of several genes coding nuclear factors (Rxrg, Nr1h3, p≤0.1), proteins involved in lipid metabolism including Pltp (p≤0.1), Lcat, and Cd36 (p≤0.05), cell death inflammation (Tnf, p≤0.1), and diabetes (Irs1, Slc2a2, p≤0.1)." (PMID 25380250, 2014). "Besides confirming functional relevance of previously reported candidate genes with diabetes, SMR analysis also identified several novel candidate genes for diabetes, such as MRPL33, ACP2, and NR1H3." (PMID 28744461, 2017).
glioma (5 papers, 2019 to 2025). A benign or malignant brain and spinal cord tumor that arises from glial cells (astrocytes, oligodendrocytes, ependymal cells). "We saw that a synthetic LXR agonist, GW396533, increased ABCA1 RNA levels but did not change either NR1H2 or NR1H3 (the genes encoding LXRβ and LXRα) in either of two different glioma lines, TS543 and TS576." (PMID 31664073, 2019). "To determine which LXR paralog was likely to be activating ABCA1 in our glioma cells, we used the UCSC Xena browser to look at expression levels of NR1H2 and NR1H3 in normal tissues in the Genotype-Tissue Expression (GTEx) data set." (PMID 31664073, 2019).
Hypercholesterolemia (5 papers, 2015 to 2023). An increased concentration of cholesterol in the blood. "We also conducted a long-term high-cholesterol dietary challenge in adults to examine the chronic effect of modulating nr1h3 gene dose on the development of hypercholesterolemia and hepatic lipid accumulation." (PMID 28536535, 2017).
liver diseases (5 papers, 2023 to 2025). "Data from experimental acute liver disease models suggest that NR1H3 performs anti-inflammatory and anti-fibrotic functions." (PMID 36768808, 2023). "Liver X receptor alpha (LXRα, NR1H3) plays a major role in regulating liver diseases." (PMID 36909161, 2023).
steatosis (5 papers, 2013 to 2023). Increased lipid within the cytoplasm of cells. "Furthermore, piglets on the astaxanthin regimen exhibited a decline in NR1H3 expression—a gene whose inhibition can foster recovery from hepatocyte steatosis, and increased expression of CYP7A1—a pivotal gene for expelling surplus liver cholesterol through bile acids." (PMID 37893992, 2023).
hepatocellular carcinoma (4 papers, 2021 to 2022). A malignant tumor that arises from hepatocytes. "First, RXRB could bind to the promoter region of NR1H3 in HepG2 hepatocellular carcinoma cells." (PMID 35957896, 2022). "Second, NR1H3 could bind to SCD in HT29 colorectal adenocarcinoma cells (no similar study was performed with hepatocellular carcinoma cells)." (PMID 35957896, 2022).
Sepsis (4 papers, 2014 to 2025). Sepsis is defined as life-threatening organ dysfunction caused by a dysregulated host response to infection. "To fully characterize the transcriptional changes and the downstream molecular events of NR1H3 deficiency that exacerbated heart failure in sepsis, we performed RNA‐sequencing experiments on hearts from septic mice of WT or NR1H3 KO." (PMID 37206244, 2023). "In general, our findings indicate that NR1H3 had a significant protective effect against sepsis and sepsis‐induced heart failure." (PMID 37206244, 2023). "Another study proved that NR1H3 was involved in the anti‐inflammatory role of Saikosaponin a on LPS‐induced sepsis." (PMID 37206244, 2023). "This was also demonstrated by the increased sepsis score and reduced anal temperature in NR1H3 knockout mice subjected to CLP." (PMID 37206244, 2023). "In particular, NLRP3 serves as a downstream effector for NR1H3‐initiated myocardial benefits during sepsis." (PMID 37206244, 2023). "In order to clarify the precise mechanisms of NR1H3 against inflammation during sepsis, we specifically focused on the inflammation‐related NLRP3 signaling pathway." (PMID 37206244, 2023). "The bioinformatics analyses revealed that LXRα (NR1H3) was downregulated in sepsis-induced ALI models and that LXRα might regulate autophagy." (PMID 40994643, 2025). "In our in vivo model of sepsis, NR1H3 knockout significantly increased ROS release." (PMID 37206244, 2023). "The primary goal of this study aimed to investigate whether NR1H3 confers cardioprotective effects against sepsis." (PMID 37206244, 2023). "Here, we hypothesized that NR1H3 mediates multiple essential sepsis‐related signalings to attenuate septic heart failure." (PMID 37206244, 2023). "To date, the role of liver X receptors α (NR1H3) in sepsis is still uncertain." (PMID 37206244, 2023). "Taken together, these results provided an overview role of NR1H3 in response to sepsis." (PMID 37206244, 2023). "Finally, RNA‐seq detection further clarified an overview of the roles of NR1H3 in sepsis." (PMID 37206244, 2023). "In this study, the protein levels of NLRP3, Caspase 1 p20, and IL‐1β in the myocardium of mice from the NR1H3‐KO + CLP group were significantly higher than those from the WT + CLP group, suggesting that NR1H3 deficiency could lead to activation of NLRP3 signaling pathways during sepsis." (PMID 37206244, 2023).
colitis (3 papers, 2021 to 2022). Inflammation of the colon. "Recently, the loss of Nr1h3 was shown to exacerbate experimental colitis, and NR1H3 expression was found to be reduced in IBD patients." (PMID 33557303, 2021). "Several nuclear receptors were specifically downregulated in males (Vdr, Lrh1/Nr5a2, Mr/Nr3c2, Rev-erbβ/Nr1d2, Car/Nr1i3, Esrrg, Lxrα/Nr1h3) and have indeed been demonstrated to regulate key protective functions relating to colitis or CRC." (PMID 36142324, 2022).
preeclampsia (3 papers, 2011 to 2022). Preeclampsia is a hypertensive disorder of pregnancy that is characterized by new-onset hypertension with proteinuria presenting after 20 weeks of gestation, and depending on mild or severe forms may initially present with severe headache, visual disturbances, and hyperreflexia. "The aim of this study was to investigate associations between the NR1H3 and NR1H2 genes and preeclampsia." (PMID 22029530, 2011). "We assessed associations between single nucleotide polymorphisms of NR1H3 (rs2279238 and rs7120118) and NR1H2 (rs35463555 and rs2695121) and the disease in 155 individuals with preeclampsia and 305 controls." (PMID 22029530, 2011). "The lack of association between the two tested NR1H3 SNPs and preeclampsia in our work is quite surprising." (PMID 22029530, 2011). "We cannot, on the basis of our results, exclude the possibility that NR1H3 is involved in the pathogenesis of preeclampsia, for two major reasons: the statistical power of this study may simply have been too low to pick up a significant association." (PMID 22029530, 2011). "One recent study revealed that the expression of NR1H3, NR1H2 and their target gene ABCA1 in JAR cells is stimulated under conditions of low oxygen concentration, mimicking the conditions occurring in preeclampsia." (PMID 22029530, 2011).
bladder cancer (2 papers, 2021 to 2024). "We found that TNFRSF12A, IL1R1, ELN and CYP26B1 were overexpressed in bladder cancer cell lines, while NR1H3 and ITIH4 were downregulated." (PMID 38216619, 2024).
breast tumor (2 papers, 2019 to 2022). "The slides showed that NR1H3 and CD68 protein were expressed in interstitial cells of breast tumor tissues." (PMID 36699456, 2022). "To test this, we examined whether expression of NR1H3/LXRA or NR1H2/LXRB correlated with expression of canonical LXR target genes (ABCA1 and APOE) in 81 ER-negative or 234 ER-positive primary breast tumours (obtained from TCGA dataset)." (PMID 31683867, 2019).
diffuse large B-cell lymphoma (2 papers, 2023). "In a related context, the role of NR1H3, encoding for the LXR-α isoform, in macrophages has been explored in diffuse large B-cell lymphomas (DLBCL)." (PMID 37780629, 2023). "Along this line, high NR1H3 gene expression marks pro-inflammatory macrophages in diffuse large B-cell lymphoma, where it predicts patient survival." (PMID 36930354, 2023). "In addition, our results suggest that LXR-dependent macrophage genes might be useful prognostic/therapeutic markers for human inflammatory diseases, a property that has already been demonstrated for NR1H3 in the case of diffuse large B-cell lymphoma." (PMID 36930354, 2023).
Hypertension (2 papers, 2023). The presence of chronic increased pressure in the systemic arterial system. "Our data first provided evidence in Chinese patients with hypertension that NR1H3 promoter variant rs11039149A>G was related to the change in SBP and the SBP response to CCBs monotherapy." (PMID 36950018, 2023).
Lupus (2 papers, 2018 to 2019). "As in pristane-induced lupus, NR1H3 and ABCA1 expression correlated in humans." (PMID 29456535, 2018). "Lupus and control Mφ did not exhibit substantially different Nr1h3 gene expression, suggesting that the low Abca1 levels in lupus mice reflect impaired activation of LXR protein rather than low Nr3h1 mRNA levels." (PMID 29456535, 2018).
melanoma (2 papers, 2023 to 2025). A malignant, usually aggressive tumor composed of atypical, neoplastic melanocytes. "Among NRs expressed in >10% of melanoma cells were NR1H3, NR3C1, NR2F6, and ESRRA." (PMID 37406115, 2023). "The results showed upregulation of NR1H3, NTHL1, and SNX1, and downregulation of DSP in melanoma compared to normal skin." (PMID 41573564, 2025).
sarcoidosis (2 papers, 2020 to 2025). Sarcoidosis is a multisystemic disorder of unknown cause characterized by the formation of immune granulomas in involved organs. "Similar to NL and NXG, sarcoidosis lesional macrophages upregulated expression of the macrophage polarization marker genes MARCO, FCGR3A, NR1H3; the ECM-encoding gene FN1; the protease-encoding gene CTSS; and genes associated with inflammation, S100A8 and CHI3L1." (PMID 39989459, 2025). "Interrogation of the expression levels of these 10 sarcoidosis genes to TB and CM DEGs revealed CCL14, CXCL9, FABP4, NR1H3 were also significantly dysregulated in TB." (PMID 33276795, 2020).
breast invasive carcinoma (1 paper, 2022). "Expression of NR1H3 was significantly lower in breast invasive carcinoma (BRCA) compared with adjacent normal tissues." (PMID 36699456, 2022).
cardiac hypertrophy (1 paper, 2023). "Against these properties, activation of NR1H3 protect against myocardial ischemia reperfusion, cardiac hypertrophy, and diabetic cardiomyopathy." (PMID 37206244, 2023).
cholestasis (1 paper, 2017). Impairment of the bile flow caused by obstruction within the liver, or outside the liver in the bile duct system. "In the cholestatic patients, an upregulation of the nuclear receptors NR1H4 (FXR) and NR1H3 (LXR) was observed in contrast to the observed downregulation in human PCLS, which could be due to the different causes of cholestasis or the large difference in time frame." (PMID 27344345, 2017).
colon adenocarcinoma (1 paper, 2022). "Moreover, the expression of NR1H3 was also significantly lower in other types of cancers compared with the corresponding normal tissues, such as colon adenocarcinoma (COAD), kidney chromophobe (KICH), lung adenocarcinoma (LUAD) and thyroid carcinoma (THCA) tissues." (PMID 36699456, 2022).
colon cancer (1 paper, 2015). "Consistent with the opposite regulation during the transition phase, NR1H3 have been reported to suppress MYC expression in colon cancer cells." (PMID 25887780, 2015).
encephalitis (1 paper, 2025). An acute inflammatory process affecting the brain parenchyma. "Nuclear Receptor Subfamily 1 Group H Member 3 (NR1H3) genes were reported to be linked with the risk of anti-NMDA receptor (anti-NMDAR) encephalitis." (PMID 40426689, 2025).
endothelial dysfunction (1 paper, 2022). In vascular diseases, endothelial dysfunction is a systemic pathological state of the endothelium (the inner lining of blood vessels) and can be broadly defined as an imbalance between vasodilating and vasoconstricting substances produced by (or acting on) the endothelium. "Different stimuli related to endothelial dysfunction, such as vascular stress, oxysterols, and inflammation, have been reported to upregulate Eng gene transcription via transcription factors Kruppel Like Factor 6 (KLF6), liver X receptor alpha (NR1H3) and NF-κB p65 (RELA)." (PMID 36160139, 2022).
heart failure (1 paper, 2023). Inability of the heart to pump blood at an adequate rate to meet tissue metabolic requirements. "Targeting NR1H3 may represent a promising approach for septic heart failure." (PMID 37206244, 2023).
hepatitis C (1 paper, 2023). "Finally 6 genes (NCOR2, NR1H3, PPARA, IRF3, MAP2K3, and TLR6) were enriched in 3 immune-related pathways, including toll-like receptor signaling pathway, EB virus infection, and hepatitis C." (PMID 37845378, 2023).
liver cancer (1 paper, 2024). An epithelial or non-epithelial malignant neoplasm that arises from the liver. "To corroborate the data, we also evaluate the expression of NR1H3, ABCG5 and ABCG8 in four different GEO datasets of human liver cancer, observing a significant reduction of their level in tumour tissue compared to non-tumoral one." (PMID 38824560, 2024).
lymph node metastasis (1 paper, 2020). "The combined expression of sterol regulatory element-binding protein 2 (SREBP2) together with HMGCR, NR1H3, and NR1H2 genes was associated with poor CRC clinical outcome independent of lymph node metastasis, distant metastasis, and advanced stage." (PMID 33194695, 2020). "Moreover, one study reports that NR1H3 and NR1H2 belong to a transcription signature associated with poor CRC clinical outcome independent of lymph node metastasis, distant metastasis, and advanced stage." (PMID 33194695, 2020).
nasopharyngeal carcinoma (1 paper, 2020). A carcinoma arising from the nasopharyngeal epithelium. "NR1H3 promotes the monocyte to macrophage transition and prolongs the length of survival in nasopharyngeal carcinoma." (PMID 33316779, 2020).
Pneumocystis infection (1 paper, 2023). "We next validated the expression of Lpcat3 and Nr1h3 in the DEX-treated or untreated mice lungs at 2 weeks post Pneumocystis infection using qPCR." (PMID 37359523, 2023).
prediabetes (1 paper, 2024). "The association of NR1H3 (encoding LXRα) and lipogenic LXR target genes, e.g., SREBF1 (encoding SREBP1, a lipogenic transcription factor), with incident prediabetes/T2D was not significant." (PMID 38747290, 2024).
renal cell carcinoma (1 paper, 2023). "In contrast, NR1H3 upregulation activates hypoxia-induced EMT, reduces the survival rate of GAC patients, and promotes the metastasis of renal cell carcinoma by regulating NOD-, LRR-, and pyrin domain-containing protein 3 inflammasomes." (PMID 37874419, 2023).
sarcoma (1 paper, 2020). A usually aggressive malignant neoplasm of the soft tissue or bone. "After performing validation in both TCGA dataset and GEO dataset GSE17679, we extracted a group of immune-related genes, including NR1H3, VAMP5, GIMAP2, GBP2, HLA-E and CRIP1 that were most significant to predict good outcomes in sarcoma patients." (PMID 33316779, 2020).
vascular malformation (1 paper, 2021). A non-neoplastic disorder that is the result of defects of vascular morphogenesis. "The missense variants identified in the NR1H3 and C23H6orf132 genes were not considered as putative causes for these vascular malformations because they were predicted to have a neutral or benign effect." (PMID 33652974, 2021).